GHRL (ghrelin and obestatin prepropeptide)
Diseases named in the same sentence as GHRL in open-access papers (continued):
Sharing a sentence is not in itself a finding about the gene and the disease.
GHRL also shares sentences with these, for which no sentence is quoted: type 2 diabetes (4 papers); depression (3); polycystic ovary syndrome (3); Cachexia (2); Hepatic fibrosis (2); liver cirrhosis (2); acute myeloid leukemia (1); adrenal carcinoma (1); adrenocorticotropic hormone deficiency (1); alcohol dependence (1); Anxiety (1); binge eating disorder (1); bipolar disorder (1); chronic hepatitis B (1); diffuse large B-cell lymphoma (1); dilated cardiomyopathy (1); eating disorder (1); Esophageal atresia (1); esophageal cancer (1); gastric ulcer (1); gastrointestinal tumors (1); glaucoma (1); Hypertension (1); hyperthyroidism (1); Infertility (1); methamphetamine dependence (1); mild cognitive impairment (1); Miscarriage (1); morbid obesity (1); Myocardial fibrosis (1).
A further 4 diseases each share a sentence with GHRL in 1 paper.